HMGB1 (high mobility group box 1)
Diseases named in the same sentence as HMGB1 in open-access papers (continued):
Sharing a sentence is not in itself a finding about the gene and the disease.
pulmonary embolism (1 paper, 2022). The obstruction of the pulmonary artery or one of its branches by an embolus, sometimes associated with infarction of the lung. "Apelin, fibulins, haemopexin, a2-macroglobulin, Ig a1-chain C region, TNF-α, HMGB1, neutrophil-to-lymphocyte ratio and albumin are among the other biomarkers whose effectiveness has been investigated in the diagnosis of pulmonary embolism." (PMID 36115957, 2022).
pyometra (1 paper, 2018). "In contrast, it should be noted that HMGB-1 concentrations peak at 72 h in dogs following ovariohysterectomy, and also increase post-operatively in dogs with pyometra." (PMID 30105229, 2018).
recessive dystrophic epidermolysis bullosa (1 paper, 2015). "HMGB1 is elevated in tumours of patients with Recessive Dystrophic Epidermolysis Bullosa, a disease characterized by chronic skin damage." (PMID 25575023, 2015).
reovirus infection (1 paper, 2021). "The induction of HMGB1 and ATP release were even more robust ICD features of reovirus infection, with the supernatants of reovirus-infected cultures containing significantly more HMGB1 and ATP than the untreated and inactivated reovirus-treated ones." (PMID 33665363, 2021).
Respiratory tract infection (1 paper, 2023). An infection of the upper or lower respiratory tract. "Reducing the level of extracellular HMGB1 induced by oxidative stress and/or respiratory tract infection could have a significant impact on protecting the lungs from injury and preserving normal physiological respiratory tract functions." (PMID 37764336, 2023).
retinal dystrophies (1 paper, 2021). "Extracellular release of the nuclear chaperone high mobility group box-1 (HMGB1), a recognized ligand of TLR2 among others, has also been implicated in various retinal dystrophies." (PMID 34360582, 2021).
rhabdomyolysis (1 paper, 2012). Necrosis or disintegration of skeletal muscle often followed by myoglobinuria. "Plasma HMGB1 levels in the rhabdomyolysis model were significantly elevated by LPS challenge, but not further elevated by xenobiotic stress; however, elevated HMGB1 levels were significantly reduced by treatment with nephrilin." (PMID 22899279, 2012). "Plasma HMGB1 levels in the rhabdomyolysis model were significantly elevated by LPS challenge, but not further elevated by xenobiotic stress; however, the elevated HMGB1 levels were significantly reduced by treatment with nephrilin." (PMID 22899279, 2012).
rheumatic heart disease (1 paper, 2013). An autoinflammatory condition following an infection with Group A Beta Hemolytic Streptococcus (GABHS), in which the heart is attacked by antibodies formed in reaction to a recent GABHS infection. "The level of HMGB1 was high prior to surgery, possibly as a result of the long-term chronic inflammatory stimulation of rheumatic heart disease." (PMID 23737912, 2013).
Sciatica (1 paper, 2013). Pain in the lower back and hip radiating in the distribution of the sciatic nerve. "In the present study, we report for the first time that etanercept significantly decreased HMGB1 expression in DRG neuron cells in a rat CCI model, which provides fresh insights into the molecular mechanism underlying the therapeutic effect of etanercept on sciatica-related nociception." (PMID 23403473, 2013).
seborrheic keratosis (1 paper, 2013). A common benign skin neoplasm usually affecting older individuals. "The expression of HMGB1 in inflammatory cells of seborrheic keratosis was also relatively strong." (PMID 23803172, 2013).
small cell neuroendocrine carcinoma (1 paper, 2024). "The effects of HMGB1 and HMGB2 silencing upon the expression of genes previously related to PCa were studied in the PCa cell line PC-3 (selected as a small cell neuroendocrine carcinoma, SCNC, PCa model not responding to hormonal treatment)." (PMID 38542079, 2024).
soft tissue sarcoma (1 paper, 2021). A malignant neoplasm arising from muscle tissue, adipose tissue, blood vessels, fibrous tissue, or other supportive tissues excluding the bones. "However, the relationship between HMGB1 and soft tissue sarcoma has received little attention." (PMID 34257571, 2021).
squamous cell tumors (1 paper, 2022). "In this study, we analyzed the release of HMGB1 from cultured tumor cells and an in vivo model of xenografted human squamous cell tumors in nude mice, in response to BPA pretreatment and neutron irradiation." (PMID 35336794, 2022).
staphylococcal infection (1 paper, 2018). An infection caused by Staphylococcus. "However, TLR4, which has been identified as the dominant inflammatory receptor for HMGB1, had no impact or very limited impact on the host response during staphylococcal infections." (PMID 29922279, 2018).
structural epilepsy (1 paper, 2020). A type of epilepsy that is conceptualized as having a distinct structural brain abnormality that has been demonstrated to be associated with a substantially increased risk of epilepsy in appropriately designed studies. "In the piriform lobe, the HMGB1-positive area in dogs with idiopathic epilepsy exceeded that in dogs with structural epilepsy by 88% (F = 2.09, p = 0.1204, Structural vs. Idiopathic p < 0.05)." (PMID 31959173, 2020). "The HMGB1-positive area was increased by 81% in animals suffering from structural epilepsy when compared to control dogs (F = 2.553, p = 0.069; CTRexp vs. Structural p < 0.05)." (PMID 31959173, 2020). "In the present study, we obtained evidence for an upregulation of HMGB1 expression in the CA1 region of dogs with idiopathic and structural epilepsy." (PMID 31959173, 2020).
T cell lymphoma (1 paper, 2020). "Elevated expression of HMGB1 may be a potential diagnostic marker for the development and progression of T cell lymphoma." (PMID 32660524, 2020). "Furthermore, the positivity rate of HMGB1 was used as an indicator for diagnosing T cell lymphoma in patients with lymph node biopsy." (PMID 32660524, 2020).
TB meningitis (1 paper, 2016). "In conclusion, our results showed that HMGB1 levels in the CSF of TBM patients were significantly higher than those in control group, non-TB meningitis, or extra neural tuberculosis." (PMID 27795917, 2016). "The mean HMGB1 value in TMB group, non-TB meningitis, extra neural tuberculosis, and control groups was 19.36, 3.12, 2.13, and 1.06 ng/ml, respectively, showing a significant difference among groups (p < 0.001)." (PMID 27795917, 2016).
Telangiectasia (1 paper, 2023). Telangiectasias refer to small dilated blood vessels located near the surface of the skin or mucous membranes, measuring between 0.5 and 1 millimeter in diameter. "HMGB1 levels were lower in patients with puffy fingers or sclerodactyly (p = 0.033) and higher in patients with telangiectasia (p = 0.027) compared to patients without puffy fingers or sclerodactyly, or telangiectasia." (PMID 37409127, 2023).
teratoma (1 paper, 2020). A non-seminomatous germ cell tumor characterized by the presence of various tissues which correspond to the different germinal layers (endoderm, mesoderm, and ectoderm). "However, the decreased levels of NANOG and SOX2 observed upon HMGB1 or HMGB1/2 double KD had no impact on the pluripotency of hESCs, as revealed using a teratoma formation assay, in which no tangible deviation from the normally differentiated teratoma morphology was demonstrated." (PMID 33076532, 2020).
thymic lymphoma (1 paper, 2015). "Here, using a similar radiation-induced thymic lymphoma model, we found the dysfunction of DCs, though HMGB1 could contribute to anticancer chemotherapy and radiotherapy via DCs33." (PMID 25923834, 2015).
tongue tumors (1 paper, 2023). "IHC staining of the ICD markers of HMGB1 and CRT in tongue tumors showed that PTT combined aPDL1 treatment led to the significantly decreased expression of HMGB1 and increased CRT exposure compared with the other groups." (PMID 36765028, 2023).
Tremor (1 paper, 2018). An unintentional, oscillating to-and-fro muscle movement about a joint axis. "PD patients with the tremor‐dominant subtype mainly had the clinical manifestation of limb tremor without obvious muscle rigidity and had serum HMGB1 and TLR4 levels of 5.08 ± 0.96 and 2.52 ± 0.72, respectively." (PMID 29670828, 2018).
tularemia (1 paper, 2016). Tularemia is an infection caused by the bacterium Francisella tularensis. "Later in pulmonary tularemia, the release of inflammatory cytokines (IL-1β, IL-6, TNFα, etc.)and DAMPs/alarmins (e.g. HMGB1, S100A9) are suggested ‘drivers’ of host death." (PMID 27015566, 2016). "In addition, during pulmonary tularemia, HMGB1 neutralization prolonged time to death, but did not protect mice." (PMID 27015566, 2016).
unstable angina pectoris (1 paper, 2013). "The serum HMGB1 level on admission was an independent predictor of cardiovascular mortality in unstable angina pectoris and non-ST segment elevation myocardial infarction." (PMID 23935732, 2013).
uterine fibroids (1 paper, 2025). "Further research is needed using biomarkers in early pregnancy, such as chorionic gonadotropin, metalloproteinases, and HMGB-1, to assess their potential for predicting women with uterine fibroids who are at higher risk of faster growth and adverse perinatal outcomes." (PMID 41227072, 2025).
VEXAS syndrome (1 paper, 2024). An adult-onset inflammatory disease that affects only males and is caused by somatic, not germline, mutations. "Serum HMGB1 levels were significantly elevated in VEXAS syndrome patients and decreased after prednisolone (PSL) dose escalation." (PMID 38854419, 2024).
viral hemorrhagic fever (1 paper, 2016). A viral infectious disease caused by RNA viruses in the Arenaviridae, Bunyaviridae, Filoviridae, or Flaviviridae family, and characterized by a severe multisystem syndrome, with damage to the vascular system and hemorrhaging. "Our results suggested that higher HMGB1 levels are a general feature of severe forms of viral hemorrhagic fevers." (PMID 27348219, 2016).
vitreous hemorrhage (1 paper, 2011). Blood extravasation in the vitreous humor. "High levels of HMGB1 were associated with the presence of vitreous hemorrhage (odds ratio=6.55; 95% CI=0.616–69.6), but the association was not statistically significant." (PMID 21850157, 2011).
Zinc deficiency (1 paper, 2020). A deficiency of the essential metal Zinc; an essential cofactor for many enzymes. "However, the detailed roles of HMGB1 and zinc deficiency in the intestinal epithelial barrier and cellular metabolism of IBD remain unknown." (PMID 33182652, 2020). "In this study, zinc deficiency caused by treatment with both TPEN and HMGB1 disrupted the epithelial barrier and induced permeability via downregulation of TJ molecules LSR, TRIC, CLDN-1 and pMAPK in Caco-2 cells in 2.5D cultures." (PMID 33182652, 2020).
tumor (1,983 papers, 2007 to 2026). "This study was the first to demonstrate the close association between extracellular HMGB1 release with the early tumor-cell-killing effect of BNCT." (PMID 41328345, 2026). "In infectious and inflammatory disorders, excessive HMGB1 release exacerbates immune dysregulation and organ damage, whereas in selected tumor settings, pyroptosis-associated HMGB1 contributes to immunogenic cell death and antitumor immunity." (PMID 42306306, 2026). "R848 is demonstrated to cause apoptosis of tumor cells, reduce tumor vasculature, and promote high mobility group box 1 (HMGB1) release features of immunogenic cell death for example, in non-breast models." (PMID 41550509, 2026). "HMGB1 is a double‐edged sword which has been linked to anti‐tumor and pro‐tumor responses after radiotherapy." (PMID 40400098, 2025). "Our findings indicated that high HMGB1 expression was associated with changes in tumor gross type, depth of invasion, lymph node metastasis, distant metastasis, and the American Joint Committee on Cancer (AJCC) stage." (PMID 40975711, 2025). "Among them, miR-129 (hsa-miR-129-2-3p) has been identified as a tumor suppressor implicated in the regulation of oncogenic pathways, including HMGB1, BCL2, and thymidylate synthase." (PMID 41157276, 2025). "Multivariate regression analysis further confirmed that age, tumor location, and HMGB1 expression were independently associated with survival (p < 0.05)." (PMID 40975711, 2025). "High-mobility group box 1 (HMGB1) is a nuclear chromatin protein overexpressed in various cancers and linked to tumor progression." (PMID 40277915, 2025). "Several studies have demonstrated the association between increased levels of HMGB1 and anti-tumor effects." (PMID 39853458, 2025). "When tumor cells undergo ferroptosis or cuproptosis, they release a series of damage-associated molecular patterns (DAMPs), such as high mobility group box 1 (HMGB1), ATP, and calreticulin (CRT)." (PMID 41201667, 2025). "Exosomes carrying high-mobility group box 1 (HMGB1) and other danger-associated molecular patterns (DAMPs) activate neutrophils, promoting tumor-associated autophagic and inflammatory signaling cascades." (PMID 40149276, 2025). "SB17170 (and its active metabolite SB1703) is a small molecule that selectively binds HMGB1 and, in immunocompetent syngeneic models, reduces circulating HMGB1 and tumor-associated MDSCs while enhancing T-cell infiltration and checkpoint blockade responses." (PMID 41465435, 2025). "The comparison with clinico-pathological parameters of a malignant tumor phenotype revealed significant associations between altered HMGB1 expression and aggressive tumor phenotype in multiple tumor entities." (PMID 40804938, 2025). "More recent studies have demonstrated that stromal cells, such as tumor-associated macrophages, upregulate intracellular HMGB1 expression upon lactate stimulation, thereby promoting cancer progression." (PMID 40148311, 2025). "During ICD, dying tumor cells release tumor-associated antigens along with danger-associated molecular patterns (DAMPs) such as calreticulin, ATP, and high-mobility group box 1 (HMGB1)." (PMID 40677710, 2025). "In cancer research, HMGB1 overexpression has been demonstrated to be closely associated with the development of multiple tumor types." (PMID 41296391, 2025). "The large size of several of our tumor cohorts enabled us to address the clinical relevance of HMGB1 deficiency in various cancer types." (PMID 40804938, 2025). "Since aspirin is an HMGB1 inhibitor, and we have shown that TLR3 activation induces TLR2 expression, it is possible that the observed effect of the HMGB1 inhibitor on tumor sphere survival is linked to TLR2 and its inability to be activated with its ligand." (PMID 40647457, 2025).
tumor (continued). "The immune system absorbs the cell debris and intracellular material (such as organelles, tumor antigens, and injury-associated molecular patterns including HMGB1) released due to the vast cell death caused by the heat shock transmission from RFA." (PMID 39871325, 2025). "It has been shown, however, that genetic deletions, promoter hypermethylation, and microRNA-mediated suppression can contribute to HMGB1 loss, and that HMGB1 deficiency can affect both tumor cell biology and tumor microenvironment." (PMID 40804938, 2025). "HMGB1 induces immunogenic cell death, activates DCs and T cells to trigger immune responses, and disrupts immune evasion mechanisms in tumor cells, thereby enhancing their susceptibility to recognition and attack by the immune system." (PMID 41354099, 2025). "Intracellular HMGB1 is predominantly associated with promoting tumor cell survival, invasion, and drug resistance." (PMID 39893499, 2025). "Whereas, during treatment, enzalutamide induced elevated levels of HMGB1 expression, recruitment and activation of tumor-associated macrophages to secrete interleukin 6 led to enzalutamide resistance." (PMID 40969278, 2025). "Regorafenib inhibits the PI3K/AKT/mTOR and RAF/MEK/ERK signaling cascades, thereby inducing immunogenic cell death in tumor cells and promoting the release of ATP, high-mobility group box 1(HMGB1), and other damage‐associated molecular patterns." (PMID 40547026, 2025). "For instance, kinase inhibitors or tumor-directed cytotoxic agents induce immunogenic cell death, leading to the release of damage-associated molecular patterns (DAMPs), such as HMGB1 and ATP, which APCs including dendritic cells and Langerhans cells." (PMID 40861456, 2025). "Compared to other groups, N@VP under X‐ray irradiation treatment caused salient overexpression of the high mobility group box 1 (HMGB1) protein in tumor tissues." (PMID 40231790, 2025). "Hmgb1/HMGB1 is expressed by ccRCC cells and myeloid cells in mouse and human tumours and Lgals9/LGALS9, encoding GALECTIN-9 is expressed by myeloid cells in both mouse and human ccRCC." (PMID 40473819, 2025). "We evaluated the association of serum HMGB1 levels with tumor response and progression-free survival (PFS)." (PMID 39853458, 2025). "In contrast, radiotherapy induces immunogenic cell death in tumor cells, during which a series of damage-associated molecular patterns, such as high-mobility group box 1 (HMGB1), calreticulin, and adenosine triphosphate, are released." (PMID 40076465, 2025). "During ICD, dying tumor cells release specific molecules known as damage-associated molecular patterns (DAMPs), including high mobility group protein B1 (HMGB1), ATP, and calreticulin (CRT), among others, into the surrounding environment." (PMID 40777132, 2025). "That a complete loss of HMGB1 expression (HMGB1 deficiency) can be found in at least one individual tumor from more than 75 different tumor categories represents a major finding of this study." (PMID 40804938, 2025). "Membrane-associated HMGB1, also referred to as amphoterin, is involved in the mediation of neurite outgrowth, smooth muscle cell chemotaxis and tumour cell metastasis." (PMID 40308590, 2025). "In cancer, extracellular HMGB1 has also been implicated in shaping the tumor immune microenvironment by modulating antigen presentation, immune suppression, and response to immunotherapies." (PMID 41465435, 2025). "Extracellular HMGB1 activates DCs and aids in tumor‐associated antigen processing through TLR4 binding." (PMID 39945555, 2025). "Its distinct advantage lies in the dual capacity for direct tumor ablation coupled with immunostimulatory effects: tumor cell lysis releases HMGB1 and tumor-associated antigens that elicit systemic CD8+ T-cell responses, thereby inducing an abscopal effect." (PMID 41415276, 2025).